IGF1 (insulin like growth factor 1)
Diseases named in the same sentence as IGF1 in open-access papers (continued):
Sharing a sentence is not in itself a finding about the gene and the disease.
adenoma (continued). "first evaluated POMT in ten previously untreated patients with invasive large adenomas, demonstrating that preoperative somatostatin receptor ligands (SRLs, e.g., SMS 201-995) markedly reduced GH and IGF-1 levels and resolved or diminished parasellar and cavernous sinus invasion." (PMID 41550875, 2025). "Considering the entire cohort, median IGF-1 levels before pasireotide (available in 57 patients) were 1.38 times the upper limit of normal (ULN) in patients with large (median size 18 mm) and invasive (82%) adenomas after failure of fg-SRL treatment." (PMID 39841390, 2025). "I consider second-generation SSAs as the first-line treatment post-surgery for any symptomatic patient with above normal IGF-1(≥1.5–2 ULN) and unresectable residual tumors, particularly in cases of hyperintense lesions on T2 on MRI or adenomas with sparsely granulated pathology." (PMID 40575269, 2025). "The regular pulsatility of LH and FSH secretion at the hypothalamic–pituitary level is altered due to elevated GH and IGF-1, resulting in a state of hypogonadotropic hypogonadism irrespective of adenoma size." (PMID 39337013, 2024). "Adenohypophysis areas and reticulin staining in pituitary tissue showed that altering the RET/apoptosis pathway induces somatotroph hyperplasia and this is enough for GH/ IGF-1 excess and gigantism, but not for generating an adenoma within our study timeframe." (PMID 34588620, 2021). "The increased bilateral ICAs distance is associated with disease duration but not with the level of GH, IGF-1 or adenoma size." (PMID 32733381, 2020). "Remission is more likely in patients with a lower GH and IGF-1 level prior to treatment, absence of adenoma in magnetic resonance image (MRI) scans, with a long-term treatment and an adequate response to low doses." (PMID 32121432, 2020). "The mean IGF-1-SD-score in 9 cured acromegalics with severe GHD in our series was significantly higher than in cured patients with nonfunctioning adenomas who had severe GHD (0.38 ± 0.95 vs. −1.43 ± 1.36)." (PMID 22918542, 2013). "However, in this patient, the GH/insulin-like growth factor-1 (IGF-1) levels had remained stable for the past 3 years, and there were no changes in the size of the primary adenoma observed on brain imaging." (PMID 38716256, 2024). "The proliferative responses to IGF-1 (Somatomedin C) and TSH, as assessed by 3H-thymidine (3H-TdR) incorporation and autoradiographic labelling index (LI), of suspension and monolayer cultures of human thyroid follicular epithelium derived from both normal and adenoma tissue have been compared." (PMID 3408641, 1988). "The analysis of the IGF1 cascade in the “surgical series” did not showed any difference in IGFBP4, IGF1 and IGF1R mRNA expression in cancer, adenomas and hyperplastic nodules compared to the respective benign counterparts." (PMID 34350538, 2022). "Our results showed significant differences in levels of serum adiponectin, IGF-1, and TNF-α in case (adenoma) and control groups (healthy normal)." (PMID 29593647, 2018). "Addition of IGF-1 (10 ng ml-1) produced no significant change in the response to TSH (0.1 mU ml-1) in 3 of these 4 adenomas, and significantly inhibited the response in the fourth adenoma." (PMID 3408641, 1988).
cognitive decline (97 papers, 2009 to 2026). "Low IGF-1 levels have been linked to severe neurological injury in acute stroke settings, cognitive decline in the elderly, and improved recovery with supplementation in animal models." (PMID 41586110, 2025). "The effects of insulin-like growth factor-1 (IGF-1) deficiency on cognitive decline have been consistently reported in animal studies, but the relationship between IGF-1 and human brain health remains controversial." (PMID 37608387, 2023). "Several studies have shown decreased IGF-1 levels in blood are associated with cognitive decline or risk of AD, and some studies found increasing IGF-1 in the serum of AD patients." (PMID 34445359, 2021). "They demonstrated that the lowest serum IGF-1 level is associated with cognitive decline in the domains of executive function, attention and verbal memory, which are mainly mediated by the prefrontal and temporal regions." (PMID 30450079, 2018). "In a 2 year prospective study, higher levels of circulating IGF1 levels were associated with reduced cognitive decline over the study period." (PMID 28203146, 2017). "Later in life, bioactive IGF-1 circulating levels are reduced, a trend that has been associated with human frailty and cognitive decline." (PMID 29311900, 2017). "This review article will then discuss the hallmarks of aging and cognitive decline associated with falls in IGF1 levels towards the end of life." (PMID 28203146, 2017). "Here, we investigated the association over time between changes in plasma levels of IGF-1 and insulin and the cognitive decline in HD patients." (PMID 27627435, 2016). "(2013)), point to potential benefits of interventions preventing age‐related IGF‐1 deficiency and promoting microvascular health for the prevention of cognitive decline in the elderly." (PMID 26172407, 2015). "Aging is associated with marked deficiency in circulating IGF‐1, which has been shown to contribute to age‐related cognitive decline." (PMID 26172407, 2015). "Identification of the mechanisms of IGF-1 actions will undoubtedly provide critical insight into regulation of brain function in general and the causes of cognitive decline with age." (PMID 23847531, 2013). "The GH/insulin-like growth factor-1 (GH/IGF-1) axis is known to be involved in aging of physiological functions including low levels associating with cognitive decline as a function of age." (PMID 19583872, 2009). "Conversely, IGF-1 was thought to decrease in elderly people in association with cognitive decline." (PMID 40141202, 2025). "In addition, an association between cognitive function and IGF-1 had also been found in neurodegenerative diseases with cognitive decline." (PMID 37638322, 2023). "In conclusion, serum IGF-1 levels might reflect the severity of cSVD and be associated with cognitive decline." (PMID 37358957, 2023). "A large number of studies in the last two decades suggest that central insulin resistance and cognitive decline in AD are associated with changes in the neuronal insulin/IR signal transduction cascade, insulin grow factor 1 (IGF-1) resistance and insulin receptor substrate 1 (IRS-1) dysregulation." (PMID 37445790, 2023). "IGF-1 and brain-derived neurotrophic factor (BDNF) deficiency have been linked to cognitive decline and dementia in older adults, whereas older adults who underwent a 24-week physical activity intervention experienced an increase in IGF-1 concomitant with improvements in cognitive function." (PMID 35436329, 2022). "Studies suggest that low IGF-1 contributing to cognitive decline may be due to nutrient deficiencies and deficient protein intake, which is commonly observed in older people." (PMID 34199148, 2021). "IGF1 levels were associated with cognitive decline in diabetic patients." (PMID 34683087, 2021). "Studies on IGF-1 factor seem very interesting for a number of reasons: First, a reduction of this factor is associated with the onset of vascular pathologies and, simultaneously, with cognitive decline." (PMID 31096580, 2019).
cognitive decline (continued). "Therefore, we aim to assess the association between changes in plasma levels of IGF-1 and insulin and the cognitive decline in HD patients over time, in a prospective multicentric cohort study." (PMID 27627435, 2016). "Besides predicting the cognitive decline in HD, IGF-1 plasma levels over time are inversely associated to the cognitive functions, independently of other confounding factors such as age." (PMID 27627435, 2016). "Serum IGF-1 concentrations might reflect an underlying biological process influencing cognitive decline based on the statistically significant correlations obtained between changes in IGF-1 levels and cognitive performance." (PMID 25713518, 2015). "Moreover,in humans, an age-related decline in IGF-1 levels occurs, and at oldage, low IGF-1 levels are associated with frailty, poornutrition and cognitive decline and anincreased risk of death." (PMID 20157552, 2009). "According with the literature, HD patients present higher basal plasma levels of IGF-1, which have been linked to the cognitive decline seen in these patients, leading to the hypothesis that IGF-1 resistance may be one of the underlying mechanisms involved in this pathology." (PMID 31231176, 2019). "In addition, higher IGF-1 level at baseline was associated with greater subsequent decline in executive function and attention and may predict cognitive decline." (PMID 27627435, 2016). "Although IGF‐1 deficiency may impact multiple aspects of neuronal function, our recent studies strongly suggest that a direct mechanistic link exists between neurovascular uncoupling and cognitive decline." (PMID 26172407, 2015). "All these prove that IGF-1 as an endocrine and metabolic index has a certain value in early prediction of cognitive decline." (PMID 39963470, 2025). "It has been reported that IGF-1 increases the number of new neurons in the hippocampus, contributing to antidepressant effects and preventing cognitive decline." (PMID 40277811, 2025). "The GH/IGF-1 system is involved in promoting longevity and regulating metabolism, while BDNF is associated with cognitive decline in patients who have had COVID-19." (PMID 40709999, 2025). "In contrast, higher baseline IGF-1 levels were linked to better performance on executive function tasks, such as the Trail Making Test B (TMT-B), in AD patients, indicating a potential protective effect of IGF-1 against cognitive decline." (PMID 40699632, 2025). "Nonetheless, different premises were explored, such as the interrelation between cortisol, insulin, or cognitive decline and IGF-1 in SZ patients." (PMID 40141202, 2025). "Previous studies indicated that SMI is a reliable predictor of functional outcomes and disability in elderly individuals, while IGF-1 is essential for neurogenesis in the adult brain and serves as a marker of cognitive decline in normal aging." (PMID 39263169, 2024). "In AD, IGF-1 blocked memory impairment in mice, and higher CSF VEGF levels were associated with healthier brain aging and slower cognitive decline in AD patients." (PMID 39200370, 2024). "This study was prompted by observations in previous research that suggested a correlation between high IGF-1 levels and cognitive decline, mainly in attention and executive function, in HD patients." (PMID 39200370, 2024). "The mechanism of IGF-1-rescued cognitive decline after mTBI likely involves the activation of various neuroprotective pathways and modulation of neuronal function in the hippocampus and other brain regions." (PMID 38028275, 2023). "IGF-1/IGF-1R knockout mice showed decreased brain size, loss of myelination, and cognitive decline, whereas overexpression of IGF-1 resulted in increased brain size and myelination." (PMID 36691085, 2023). "In idiopathic Parkinson’s disease, IGF-1 resistance—characterized by elevated levels of circulating IGF-1 and diminished IGF-1 function—is linked to disease progression and cognitive decline." (PMID 37803329, 2023).
cognitive decline (continued). "IGF-1 drop seen in old age became a subject of research and emerging evidence suggests potential therapeutic interventions aimed at boosting cognitive decline and addressing neuronal regeneration via IGF-1 upregulation." (PMID 35563873, 2022). "Studies also show that a decrease in the plasma IGF1 level can predict cognitive decline in AD, and the elevation of IGF1 mediates the environment enrichment- and exercise-induced beneficial effects on the central nervous system." (PMID 30867903, 2019). "IGF-1 expression is high at young age and declines during aging, and this reduction correlates with cognitive decline in the elderly." (PMID 31096580, 2019). "Insulin-like-growth-factor-1 on the other hand, has been shown to decline with age and precede cognitive decline." (PMID 31128067, 2019). "This would strengthen central cholinergic acetylation enzyme activity and increase insulin-like growth factor-1 expression, leading to the maintenance of cholinergic nerve function and attenuating cognitive decline as seen in rats with cognitive dysfunction." (PMID 30100873, 2018). "We assessed their cognitive decline using the Unified Huntington’s Disease Rating Scale, and their IGF-1 and insulin plasmatic levels, at baseline and once a year during the follow-up." (PMID 27627435, 2016). "Only in HD male patients, the high levels of IGF-1 were correlated with increased cognitive decline." (PMID 25140802, 2014). "To date, the importance of adequate levels of IGF-1 for maintenance of brain health has been established for rodents, non-human primates, and humans, supporting the fundamental role of IGF-1 in aging and, more specifically, cognitive decline." (PMID 23847531, 2013). "Because of the important association between age-related cerebrovascular impairments and cognitive decline, the potential neuroprotective effects of IGF-1 are considered as partially mediated through cerebromicrovascular protection." (PMID 23847531, 2013). "It was suggested that IGF-1 increase might indicate a cognitive decline based on recent reports in Huntington’s disease." (PMID 40141202, 2025). "IGF-1 increase could be indicating an incipient cognitive decline in SZ patients since previous studies have shown a significant increase in IGF-1 in SZ patients in early stages of Alzheimer’s (AD) and Parkinson’s diseases." (PMID 40141202, 2025). "This indicates that reducing IGF-1 levels may lead to dysfunction in these regions, further contributing to memory impairment and cognitive decline." (PMID 39335481, 2024). "Recent research also suggests that systematic exercise could counteract cognitive decline by triggering the release of neurotrophic factors such as insulin-like growth factor (IGF-1)." (PMID 39407758, 2024). "IGF-1 is the central mediator for GH activity and promotes neuroprotective effects; lower serum levels of IGF-1, which are common in the elderly, are associated with cognitive decline." (PMID 37445790, 2023). "In natural condition, plasma IGF-1 reaches a peak (approximately 52 nmol/L) around puberty and then declined progressively to approximately 13 nmol/L by the age of 75 years, in parallel with the age-related cognitive decline." (PMID 37608387, 2023). "- Circulating IGF-1 is involved in cognitive decline in normal aging and dementia." (PMID 35832183, 2022). "Specifically, mounting evidence in the older adult suggests that reductions in circulating IGF-1 signaling are involved in cognitive decline during the normal aging process and could serve as a biomarker of cognitive aging." (PMID 35832183, 2022). "The third set includes blood neurotrophic biomarkers (e.g., brain-derived neurotrophic factor [BDNF], insulin-like growth factor 1 [IGF-1], and short-chain acylcarnitines [SCACs]) that are found to promote neurogenesis and protect against cognitive decline and incident AD." (PMID 31907024, 2020).
cognitive decline (continued). "Consequently, loss of insulin/IGF-1 signaling in the brain, mediated by both the IR and the IGF1R, has generally been associated with an elevated risk of AD, cognitive decline, (premature) dementia, depression, and anxiety." (PMID 32226608, 2020). "Furthermore, individuals with cognitive decline typically have lower levels of insulin-like growth factor 1 (IGF-1)." (PMID 33137993, 2020). "In conclusion, taken together, in the present study of the Ukrainian cohort, higher serum IGF-1 concentrations were associated with MDD status (in the age cohort of 18–54 years old), the severity of hypothymia, anxiety, and cognitive decline (predominantly executive dysfunction)." (PMID 32384884, 2020). "Our findings support the idea that IGF-1 levels may hold predictive value for the stratification of ARHL and, secondary to hearing loss, for cognitive decline." (PMID 29311900, 2017). "Our findings, taken together with the results of earlier studies, point to potential benefits of interventions preventing age‐related decline in circulating IGF‐1 levels and promoting microvascular health for prevention of CMHs and cognitive decline in the elderly." (PMID 28295976, 2017). "In addition, it would be interesting to further investigate the role of the downstream PIK3/Akt pathway in resistance to IGF-1 on one hand and in the cognitive decline in HD on the other hand." (PMID 27627435, 2016). "Seen that IGF-1 resistance is involved in cognitive decline in HD, the control of IGF-1 may lead to a new therapeutic approach." (PMID 27627435, 2016). "In addition, the correlation of IGF-1 levels with other clinical presentations, e.g., cognitive decline, hyposmia, psychological symptoms, or rapid eye movement sleep behavior disorder (RBD), remain to be explored." (PMID 26657015, 2015). "In addition, serum levels of the insulin growth factor 1 (IGF-1) and epidermal growth factor (EGF) are associated with cognitive decline in early stage and drug-naïve patients with PD." (PMID 26566043, 2015). "Both brain insulin and IGF1 resistance are considered an early and common feature of AD, which seem to be closely associated with the IRS-I dysfunction triggered by Aβ oligomers that promote cognitive decline." (PMID 25346723, 2014). "Infants with ISs of unknown etiology often have CSF IGF-1 values comparable to controls and respond well to ACTH, whereas children with spasms following early structural insults show markedly reduced CSF IGF-1, poor hormonal response, and later cognitive decline." (PMID 41470225, 2025). "RT may help mitigate cognitive decline in healthy older adults, potentially through IGF-1." (PMID 40381170, 2025). "We hypothesized that cognitive function would be reduced due to stress-related structural changes in the brain, and this cognitive decline was expected to be reflected by a decrease of neurotrophic factors BDNF and IGF-1, as these factors are highly associated with cognitive function." (PMID 36798941, 2023). "Moreover, the significant low levels of IGF-1 might also have an impact on the cognitive decline seen at 7 and 14 days." (PMID 36671407, 2022). "As social deprivation in childhood can lead to deficits in IGF-1 (see Johnson and Gunnar, 2011 for a review), suppression of IGF-1 may constitute a pathway whereby adverse attachment experience related to early life stress can exacerbate age-related cognitive decline." (PMID 31333443, 2019). "Moreover, if higher IGF-1 levels indeed indicate future cognitive decline, then previous studies in healthy older subjects may have inadvertently excluded those with high IGF-1 levels." (PMID 27115487, 2016). "Thus, our results support the hypothesis that resistance to IGF-1 is related to the cognitive decline in patients with HD; and are in line with previous findings on HD." (PMID 27627435, 2016).